TST (thiosulfate sulfurtransferase)
Description:
Catalyzes the transfer of sulfur ion from thiosulfate to cyanide, although other thiol compounds, besides cyanide, can act as sulfur ion acceptors (By similarity). It also has weak mercaptopyruvate sulfurtransferase (MST) activity (By similarity). Has a pivotal role in cyanide detoxification. Together with MRPL18, acts as a mitochondrial import factor for the cytosolic 5S rRNA. Only the nascent unfolded cytoplasmic form is able to bind to the 5S rRNA.
Synonyms: RDS
Tractability: PROTAC: ubiquitination databases record sites on it; its protein half-life has been measured; a small molecule that binds it is known.
Target class: Enzyme; Transferase
Gene: Protein-coding gene on chromosome 22 (37,010,859 to 37,024,797, reverse strand). Ensembl gene ENSG00000128311.
Subcellular location: Mitochondrion; Mitochondrion matrix
Subcellular location (Human Protein Atlas): Mitochondria
Pathways (Reactome):
Metabolism: Degradation of cysteine and homocysteine; Sulfide oxidation to sulfate
Gene Ontology:
Molecular function: 5S rRNA binding; thiosulfate-cyanide sulfurtransferase activity; sulfurtransferase activity
Biological process: cellular detoxification of nitrogen compound; epithelial cell differentiation; rRNA import into mitochondrion; rRNA transport; cyanate catabolic process; sulfur amino acid catabolic process
Cellular component: extracellular region; mitochondrion; mitochondrial matrix
Genetic constraint (gnomAD): Loss-of-function variants: 25 observed, 23.61 expected, observed/expected ratio (o/e) 1.06, 90% interval 0.77 to 1.48. The upper end of that interval is the gene's LOEUF score, 1.48, which puts it in group 6 of 6, group 1 being the genes least tolerant of losing a copy. Missense variants: 392 observed, 400.56 expected, observed/expected ratio (o/e) 0.98, 90% interval 0.9 to 1.06. Synonymous variants: 187 observed, 167.62 expected, observed/expected ratio (o/e) 1.12, 90% interval 0.99 to 1.26.
Homologues: Orthologues: chimpanzee TST (99% identical), macaque TST (98% identical), dog TST (92% identical), mouse Tst (91% identical), rat Tst (91% identical), guinea pig TST (91% identical), pig TST (90% identical), rabbit TST (71% identical), tropical clawed frog XB996291 (59% identical), tropical clawed frog tst (59% identical), zebrafish mpst (56% identical), Caenorhabditis elegans mpst-6 (27% identical), and 5 more. Paralogues in human: MPST (60% identical).
Diseases named in the same sentence as TST in open-access papers:
TST is named in the same sentence as 31 diseases in open-access papers, as found by Europe PMC text mining. Sharing a sentence is not in itself a finding about the gene and the disease. The quoted sentences say what the papers report.
colon cancer (2 papers, 2012 to 2022). "A significant increase in TST activity and expression was observed in human cancer cell line HT-29 in advanced colon cancer, where the expression of both thiosulfate sulfurtransferase and mercaptopyruvate sulfurtransferase was markedly reduced." (PMID 35955583, 2022).
diabetes (2 papers, 2017 to 2022). "Recently, mouse thiosulfate sulfurtransferase (TST) protein was proposed to have obesity-resistance and anti-diabetes effects in mammals." (PMID 28830344, 2017).
ulcerative colitis (2 papers, 2012 to 2025). An inflammatory bowel disease involving the mucosal surface of the large intestine and rectum. "For example, quantitative analysis of colonic biopsies from ulcerative colitis (UC) patients revealed significantly reduced activity and gene expression of thiosulfate sulfurtransferase (TST), a key enzyme in the H2S-oxidation pathway, compared to controls." (PMID 40732998, 2025).
acute leukemia (1 paper, 2024). A clonal (malignant) hematopoietic disorder with an acute onset, affecting the bone marrow and the peripheral blood. "Thiosulfate sulfurtransferase shows limited expression and activity in CD4+ and CD8+ lymphocytes and some ALL cell lines, with the TST gene identified as a valuable target for distinguishing acute leukemias." (PMID 39062461, 2024).
colitis (1 paper, 2022). Inflammation of the colon. "Studies on the other enzymes, namely ETHE1, TST and SQOR, all show a lower expression in human and in animal colitis samples." (PMID 36421421, 2022).
colorectal cancer (1 paper, 2021). A primary or metastatic malignant neoplasm that affects the colon or rectum. "We suggested for the first time that downregulation of mitochondrial genes, including ETHE1, SQOR, TST, and GPX3, would help colorectal cancer cells to produce more energy under hypoxic conditions through mechanisms that are different from “Warburg Effect”." (PMID 34249670, 2021).
diabetic kidney disease (1 paper, 2025). Progressive kidney disorder caused by vascular damage to the glomerular capillaries, in patients with diabetes mellitus. "Furthermore, in diabetic kidney disease (DKD), TST deficiency contributes to the disruption of fatty acid oxidation (FAO), a critical process for energy production in renal tubular cells." (PMID 40107018, 2025).
Friedreich ataxia (1 paper, 2025). An inherited condition that affects the nervous system and causes movement problems. "In the brain, TST deficiency is linked to neurodegenerative conditions like Leber's Hereditary Optic Neuropathy (LHON) and Friedreich's ataxia (FRDA), where downregulated TST disrupts mitochondrial function and redox balance." (PMID 40107018, 2025).
Herpes simplex (1 paper, 2021). "Herpes simplex virus-1 (HSV-1) infection depletes the levels of RNA binding proteins (RBPs) (thiosulfate sulfurtransferase (TST), mitochondrial ribosomal protein L18 (MRPL18)) that typically shield pseudogene 5S rRNA (RNA5SP141)." (PMID 33444401, 2021).
inflammatory bowel disease (1 paper, 2025). A spectrum of small and large bowel inflammatory diseases of unknown etiology. "In the colon, decreased TST expression is observed in inflammatory bowel disease (IBD), potentially reducing H2S detoxification, compromising the mucosal barrier, and increasing inflammation." (PMID 40107018, 2025).
leukemia (1 paper, 2022). A malignant (clonal) hematologic disorder, involving hematopoietic stem cells and characterized by the presence of primitive or atypical myeloid or lymphoid cells in the bone marrow and the blood. "In different types of leukemia cell lines, such as REH, DND-41, MOLT-4, MV4-11, MOLM-14, and K562, gene expression for TST, MPST, CBS, and CTH was studied on the mRNA and protein level." (PMID 35204649, 2022). "In conclusion, our findings showed significant differences in the expression of TST, MPST, CTH, and CBS in different types of human leukemia cells." (PMID 35204649, 2022). "In the present paper, we investigated the expression of TST, MPST, CTH, and CBS in the different types of human leukemia cell lines: B-ALL (REH cells), T-ALL (DND-41 and MOLT-4 cells), AML (MV4-11 and MOLM-14 cells), and CML (K562 cells)." (PMID 35204649, 2022).
melanoma (1 paper, 2023). A malignant, usually aggressive tumor composed of atypical, neoplastic melanocytes. "In this research paper, we examined the expression levels of sulfurtransferases (MPST, TST, CTH) and cystathionine beta-synthase in human primary (WM115) and metastatic (WM266-4) melanoma cell lines both in normoxic and hypoxic conditions." (PMID 37892173, 2023). "Thus, it seems that MPST can play an important role in the progression of human melanoma cells (WM115 and WM266-4) compared to other sulfurtransferases such as TST and CTH, of which, expression in both cell lines was not changed." (PMID 37892173, 2023).
typhoid fever (1 paper, 2013). A bacterial infectious disorder contracted by consumption of food or drink contaminated with Salmonella typhi. "This worked revealed that parallel deletion of glpE and pspE genes decreased virulence of S. Typhimurium in the mouse model of typhoid fever, suggesting a role of TST activity in systemic infection." (PMID 23940650, 2013).
cancer (4 papers, 2014 to 2024). A tumor composed of atypical neoplastic, often pleomorphic cells that invade other tissues. "Among the 102 feature genes, eight genes (MYLK, GADD45A, ACADM, UQCR11, TST, PTCD3, SOD1, CD151) were significantly enriched in the cancer hallmark of adipogenesis." (PMID 36905391, 2023). "GREAT also reported that HepG2-enriched windows were close to many cancer genes HPX, HPN, LCAT, TST, GSTM1, CEPBA, CYP2B6." (PMID 25522020, 2014). "Notably, the levels of expression of these genes, added to six other genes involved in mitochondria activity (TST, NSUN3, GLMP and PTCD2), were reduced following the expression of HLA-G in the RCC7 cells, consistent with mitochondrial impairment found in many types of cancer, particularly in ccRCC." (PMID 39358558, 2024).
tumor (3 papers, 2015 to 2025). "Contrary to a previous study describing decreased levels of enzymes in the respiratory chain in malignant adrenal tissue, our 2D-DIGE analysis could detect only one downregulated protein in tumor condition: thiosulfate sulfurtransferase (TST)." (PMID 25691058, 2015).
infection (2 papers, 2010 to 2020). The state of being infected such as from the introduction of a foreign agent such as serum, vaccine, antigenic substance or organism. "On Western blot analysis, rTsT was identified using anti-his tag monoclonal antibody (McAb), infection serum and anti-TsT serum." (PMID 32764274, 2020). "Western blotting showed rTsT was identified by infection serum and anti-TsT serum." (PMID 32764274, 2020).
TST also shares sentences with these, for which no sentence is quoted: glioblastoma (2 papers); acute lymphoblastic leukemia (1); astrocytoma (1); brain cancer (1); co-infection (1); Encephalopathy (1); gastric cancer (1); glioma (1); Hypertension (1); latent infection (1); Leber hereditary optic neuropathy (1); low grade glioma (1); Obesity (1); schizophrenia (1); triple-negative breast carcinoma (1).